B2M (beta-2-microglobulin)
Diseases named in the same sentence as B2M in open-access papers (continued):
Sharing a sentence is not in itself a finding about the gene and the disease.
cryoglobulinemia (2 papers, 2015 to 2025). Cryoglobulinemia is a type of vasculitis that is caused by abnormal proteins (antibodies) in the blood called 'cryoglobulins.' At cold temperatures, these proteins become solid or gel-like, which can block blood vessels and cause a variety of health problems. "Laboratory predictors include hypocomplementemia (particularly low C4 and C3), cryoglobulinemia, cytopenias, monoclonal gammopathy, and elevated beta-2-microglobulin." (PMID 41531558, 2025). "It has also been shown to correlate with B cell biomarkers of disease activity such as beta-2 microglobulin, serum free light chains of immunoglobulins, the cytokine BAFF and FMS-like tyrosine kinase 3 ligand levels, as well as with cytopenias, hypocomplementemia and cryoglobulinemia." (PMID 25723713, 2015).
Down syndrome (2 papers, 2024). "The genetic elimination of B2M or the systemic application of an anti-B2M antibody effectively mitigates synaptic impairments in mice with Down syndrome." (PMID 38836960, 2024). "Furthermore, the implication of B2M in various other diseases has been suggested, as evidenced by the induction of synaptic and memory defects in mice with Down syndrome after the systemic administration of B2M." (PMID 38836960, 2024). "In addition, using the Down syndrome model, a recent study found that B2M acted as a neuronal NMDA receptor antagonist to impair neuronal synaptic function and cognitive ability in mice independently of the MHC-I molecule." (PMID 38743119, 2024).
follicular lymphoma (2 papers, 2016 to 2025). Follicular lymphoma is a form of non-Hodgkin lymphoma characterized by a proliferation of B cells whose nodular structure of follicular architecture is preserved. "This change was made because B2M is considered a more specific and sensitive marker of tumor burden and cell turnover in follicular lymphoma, especially with modern treatments." (PMID 40075894, 2025).
glomerulonephritis (2 papers, 2021 to 2023). A renal disorder characterized by damage in the glomeruli. "Furthermore, in the cluster of the podocyte, three glomerulonephritis related genes named FXYD5, CD74 and B2M were found." (PMID 33754492, 2021).
goiter (2 papers, 2014 to 2020). Enlargement of the thyroid gland usually caused by lack of iodine in the diet, hyperthyroidism, or thyroid nodules. "In conclusion, the results of the present study suggest that ACTB gene is more stable than SDHA, GAPDH, HPRTI, YWHAZ, and B2M when evaluating human normal thyroid and goiter together." (PMID 24900955, 2014).
HCMV infection (2 papers, 2016 to 2025). "In order to explore the possible role of HLA-G molecules in congenital HCMV infection, we analyzed maternal and fetal sHLA-G and b2M expression in correlation with the risk of transmission and severity of HCMV infection." (PMID 27699182, 2016). "In this work we investigated the expression of soluble (s)HLA-G and beta-2 microglobulin (component of HLA) molecules in correlation with the risk of transmission and severity of congenital HCMV infection." (PMID 27699182, 2016). "Similarly, several human mRNAs also displayed increased G-incorporation rates following HCMV infection including B2M-211 and HSP9011A-201." (PMID 41446155, 2025). "On the contrary, beta-2 microglobulin levels were only slightly higher in maternal serum from pregnant women with primary HCMV infection than in nonprimary and uninfected, respectively (p = 0.12 and p = 0.06)." (PMID 27699182, 2016). "In this work, we analyzed the levels of sHLA-G and b2M molecules in the maternal serum samples and showed that sHLA-G median levels were significantly higher in maternal serum from pregnant women with primary HCMV infection than in nonprimary and uninfected, respectively (p < 0.001 and p < 0.006)." (PMID 27699182, 2016). "We evaluated sHLA-G and b2M levels in sera of 130 pregnant women, 30 uninfected, 56 with primary HCMV infection, and 44 with nonprimary HCMV infection, and 52 nonpregnant women with HCMV past infection." (PMID 27699182, 2016).
hyperlipidemia (2 papers, 2024 to 2025). "Metabolic profiling revealed hyperlipidemia in 49.8% of cases (269/540), with beta-2 microglobulin (β2-MG) abnormalities being the most common laboratory derangement (21.9%, 118 cases)." (PMID 40937180, 2025).
hypoalbuminaemia (2 papers, 1993 to 2016). "On univariate analysis, hypoalbuminaemia, hyponatremia and beta 2 microglobulin (> 3) correlated with unfavourable outcome in terms of duration of remission (P = 0.0009, 0.007 and 0.04 respectively)." (PMID 8398705, 1993).
hypopharyngeal carcinoma (2 papers, 2021 to 2023). Carcinoma, predominantly squamous cell, arising from the epithelial cells of the hypopharynx. "Recently, B2M was validated as a key reference gene in laryngeal and hypopharyngeal cancers, highlighting its suitability for investigating target gene expression." (PMID 33917480, 2021).
immune deficiencies (2 papers, 2024 to 2025). "Pathogenic single-nucleotide variants in B2M have been found in immunodeficiency and in visceral amyloidosis with polyneuropathy." (PMID 38891944, 2024). "These immune deficiencies may underline the poor DFS observed in dCRT-treated ARID1A/B2M-mutant patients." (PMID 40536270, 2025).
infertile (2 papers, 2023 to 2025). "Beta-2-microglobulin (B2M) is a component of the MHC-I molecule in many species and may contribute to inter-species infertility and speciation." (PMID 41303481, 2025).
influenza (2 papers, 2016 to 2021). An acute viral infection of the respiratory tract, occurring in isolated cases, in epidemics, or in pandemics; it is caused by serologically different strains of viruses (influenzaviruses) designated A, B, and C, has a 3-day incubation period, and usually lasts for 3 to 10 days. "Here, we demonstrate that after influenza infection, MHC-I expression on lung epithelial cells is upregulated, and mice bearing unlicensed NK cells (Ly49-deficient NKCKD and MHC-I-deficient B2m-/- mice) survive the infection better than WT mice." (PMID 26928844, 2016). "Specifically, influenza samples maintained higher levels of type I IFN response–associated antiviral ISGs (e.g., IFITM1, IFITM2, IFITM3, OAS2, OAS3, OASL) and antigen presentation genes (e.g., HLA-DRB5, HLA-C, B2M, HLA-B, HLA-E)." (PMID 34618691, 2021). "Protection conferred by the blocking of Ly49C/I receptors was smaller compared to the lack of Ly49 receptors (NKCKD) or MHC-I ligands (B2m-/-), possibly because of a suboptimal blocking in these experiment or the involvement of other inhibitory MHC-I receptors in influenza immunoevasion." (PMID 26928844, 2016).
liver cirrhosis (2 papers, 2022 to 2024). "Additionally, B2M, a component of the HLA class I molecule and a potential biomarker for liver cirrhosis, has been identified as a connector, as well as CD19, a marker for B-lymphocytes." (PMID 36458021, 2022). "TOPAS identified 11 connectors for 20 seed/query genes, 2 of which (i.e. B2M and PDGFR) were previously shown to be relevant in liver cirrhosis, demonstrating its utility in constructing biologically connected disease modules from a sparse and incomplete gene set." (PMID 39530220, 2024).
lymph node enlargement (2 papers, 2017 to 2023). "Through this retrospective study, we have concluded that in patients presenting with lymph node enlargement, levels of cytokines, B2M and IgG can be used to predict malignancies." (PMID 29228708, 2017).
monoclonal gammopathy (2 papers, 2025). A condition characterized by the abnormal presence of monoclonal immunoglobulins in the blood or urine. "Additionally, the elevated beta-2 microglobulin, kappa and lambda light chains, and immunoglobulin levels raise potential concerns for an underlying monoclonal gammopathy or broader immune dysregulation." (PMID 40007921, 2025).
nasopharyngeal carcinoma (2 papers, 1992 to 2024). A carcinoma arising from the nasopharyngeal epithelium. "Serum beta-2-microglobulin (beta 2M) levels of 274 Chinese patients with different stages of nasopharyngeal carcinoma at presentation and that of 35 patients who developed distant metastases post-treatment were assayed." (PMID 1520593, 1992).
oral cavity squamous cell carcinoma (2 papers, 2020 to 2021). A squamous cell carcinoma arising from the oral cavity. "For example, knockdown of B2M expression has been shown to inhibit tumor cell migration and invasion in oral cavity squamous cell carcinoma." (PMID 33960680, 2021). "The present study aims to compare beta-2 microglobulin levels in patients with lichen planus of the esophagus, oral squamous cell carcinoma, and healthy individuals." (PMID 32552881, 2020). "Their study confirmed that beta-2 microglobulin can be applied as an indicator of the tumor for oral squamous cell carcinoma." (PMID 32552881, 2020).
osteoarthritis (2 papers, 2020 to 2021). A noninflammatory degenerative joint disease occurring chiefly in older persons, characterized by degeneration of the articular cartilage, hypertrophy of bone at the margins and changes in the synovial membrane. "B2m, a component of MHC class I molecules for monitoring inflammatory reaction, is highly expressed in osteoarthritis (OA) patients than controls, regardless of OA stage." (PMID 33752715, 2021).
osteoporosis (2 papers, 2017 to 2022). A condition of reduced bone mass, with decreased cortical thickness and a decrease in the number and size of the trabeculae of cancellous bone (but normal chemical composition), resulting in increased fracture incidence. "Despite OVX with deficient diet, glucocorticoid proved to be the most suitable osteoporosis model in sheep, and it was recommended to test B2M, GAPDH, RPL19, and YWHAZ gene expression that represented standard reference genes for a relative quantification of transcriptional activity of ovine bone." (PMID 36012173, 2022). "Based on our data we recommend testing of B2M, GAPDH, RPL19, and YWHAZ for relative quantification of gene expression studies in ovine bone which it is a robust bio-medical model for evaluating bone-substituents in osteoporosis." (PMID 29258442, 2017).
prion disease (2 papers, 2012 to 2024). A transmissible disease that is caused by a protein that is able to induce abnormal folding of normal cellular proteins, leading to characteristic spongiform brain changes, which are associated with neuronal loss without an inflammatory response. "The possible mechanistic links of the remaining genes in the SCC (TLR2, NCF1, PTPN6 and B2M) to prion disease are still open." (PMID 23068602, 2012).
prostate small cell carcinoma (2 papers, 2019 to 2021). A neuroendocrine carcinoma of the prostate gland with unfavorable prognosis, composed of small cells containing neurosecretory granules. "Like stem cells, prostate small cell carcinoma express this quartet of scTF as well as a 10-fold lower level of β2-microglobulin (B2M) than that of differentiated cell types." (PMID 34911496, 2021). "Prostate small cell carcinoma exhibits characteristics of stem cells, including poor differentiation (e.g., loss of epithelial cell density, non-luminal-like) and lower B2M expression due to the reactivation of stem cell transcription factors." (PMID 31146720, 2019).
sarcopenia (2 papers, 2024 to 2025). Progressive decline in muscle mass due to aging which results in decreased functional capacity of muscles. "The risk of sarcopenia and poor muscle outcomes according to serum B2M levels in older adults was assessed by logistic regression analyses." (PMID 40026116, 2025). "Association of presence of sarcopenia or abnormalities in sarcopenia parameters with serum B2M level by logistic regression analysis." (PMID 40026116, 2025). "Further meticulously designed large‐scale longitudinal studies are imperative to confirm the role of circulating B2M as a blood‐based biomarker for predicting the risk of sarcopenia." (PMID 40026116, 2025). "Individuals who had beta-2 microglobulin levels below 2.26 mcg/mL were found to have a 10.75 times higher risk of sarcopenia." (PMID 39597064, 2024). "The optimal cut-off value for serum beta-2 microglobulin level was 2.26 mcg/mL, and values lower than this point were found to be diagnostic for sarcopenia." (PMID 39597064, 2024). "A particularly intriguing finding in our clinical study is that serum B2M levels were primarily associated with muscle strength and physical performance, showing limited correlation with muscle mass, among the diagnostic criteria for sarcopenia." (PMID 40026116, 2025). "Given that sarcopenia is a key phenotype of ageing, we conducted current experiments and found that recombinant B2M inhibited in vitro myogenesis, induced myotube atrophy and decreased muscle size, muscle strength and physical performance in mice." (PMID 40026116, 2025). "Linear regression analyses were conducted to explore the relationship of serum B2M levels with specific muscle parameters relevant to sarcopenia." (PMID 40026116, 2025). "To clarify the potential role of B2M in muscle metabolism, we investigated the effects of B2M on in vitro and animal muscle biology and its clinical relevance for sarcopenia parameters in older adults." (PMID 40026116, 2025). "Differences in serum B2M levels according to status of sarcopenia and related specific component were evaluated using ANCOVA before and after adjustment for confounding factors." (PMID 40026116, 2025). "To elucidate the role of B2M in sarcopenia, we first examined its tissue‐specific expression in skeletal muscle using publicly available datasets from human and murine models." (PMID 40026116, 2025). "The analysis revealed an age‐dependent increase in B2M expression, indicating its potential involvement in the pathogenesis of sarcopenia." (PMID 40026116, 2025). "As part of our efforts to uncover potential factors contributing to the development of sarcopenia, we have been particularly focused on exploring the role of B2M in muscle metabolism." (PMID 40026116, 2025). "This study aimed to determine the prevalence and investigate the role of serum beta-2 microglobulin level as a biomarker for diagnosing sarcopenia." (PMID 39597064, 2024). "To explore this hypothesis, we conducted a comprehensive investigation into the impact of B2M on cellular and animal muscle biology, as well as its clinical implications concerning sarcopenia parameters in older individuals." (PMID 40026116, 2025). "β2‐Microglobulin (B2M) has garnered considerable interest as a potential pro‐ageing factor, leading to speculation about its involvement in muscle metabolism and the development of sarcopenia, a key component of ageing phenotypes." (PMID 40026116, 2025). "In a clinical study, serum B2M levels were inversely associated with grip strength, usual gait speed and short physical performance battery (SPPB) total score after adjustment for age, sex, and body mass index, whereas sarcopenia phenotype score showed a positive association." (PMID 40026116, 2025). "However, in this multivariable adjustment model, serum B2M concentrations were no longer different between those with and without sarcopenia or prolonged chair stand test time." (PMID 40026116, 2025).
Sjögren’s Syndrome (2 papers, 2017 to 2023). "The aim of this study was the assessment of the relationship between endothelial dysfunction and serum cytokines, anti-SSA and anti-SSB antibodies, beta-2 microglobulin levels, focus score, and EULAR Sjögren’s Syndrome Disease Activity Index (ESSDAI) in pSS patients." (PMID 37762225, 2023).
small cell carcinoma (2 papers, 2021 to 2024). A neuroendocrine carcinoma composed of small malignant cells which are often said to resemble "oat cells" under the microscope. "PENK can down-regulate scTF and up-regulate B2M in stem-like small cell carcinoma LuCaP 145.1 cells indicative of exit from the stem state and differentiation." (PMID 38595814, 2024). "The neoR LuCaP 145.1 cells showed downregulation of scTF and upregulation of B2M, a response indicative of PENK being able to single-handedly alter the differentiation state of stem-like small cell carcinoma by targeting scTF." (PMID 38595814, 2024). "Using small cell carcinoma LuCaP 145.1 as a stem-like cell type, we showed that PENK could induce these cancer cells to undergo differentiation with down-regulation of scTF and simultaneously up-regulation of B2M." (PMID 34911496, 2021). "Small cell carcinoma LuCaP 145.1 in the stem-like grouping expresses stem cell transcription factors (scTFs) such as the core quartet of LIN28A, NANOG, POU5F1, and SOX2, as well as a low level (10-fold less) of β2-microglobulin (B2M) compared to the levels by non-stem cells." (PMID 38595814, 2024).
tubulointerstitial nephritis (2 papers, 2019 to 2025). "An elevated beta-2 microglobulin level discovered by the urinalysis during admission raised the suspicion of tubulointerstitial nephritis caused by glyphosate." (PMID 39073524, 2025).
viral myocarditis (2 papers, 2025). Myocarditis that is caused by an infection with a viral agent. "Ultimately, four overlapping features, namely, B2M, C3, CFB, and CASP12, were selected as potential biomarkers for viral myocarditis using both algorithms." (PMID 40230577, 2025).
acute pancreatitis (1 paper, 2016). An acute inflammatory process that leads to necrosis of the pancreatic parenchyma. "The expression levels of ACTB, TUBB, and B2M were found to be significantly upregulated during acute pancreatitis, whereas the expression level of 18sRNA was downregulated." (PMID 27069927, 2016). "Because of its enriched expression in immunocytes, variation in B2M mRNA expression may correspond to the infiltration of leukocytes into pancreatic tissues at different stages of acute pancreatitis, according to the cell composition in the inflammatory tissue." (PMID 27069927, 2016). "The mRNA expression of B2M and HPRT1 in pancreatic tissues remained constant between the control group and MAP group, which indicated that B2M and HPRT1 are appropriate reference genes for caerulein-induced acute pancreatitis." (PMID 27069927, 2016). "In studies of caerulein-induced murine acute pancreatitis, ACTB, GAPDH, 18sRNA, beta-2 microglobulin (B2M), and hypoxanthine phosphoribosyltransferase 1 (HPRT1) have been frequently used as reference genes for comparison of mRNA transcription in pancreatic tissue." (PMID 27069927, 2016).
Allergy (1 paper, 2017). An allergy is an immune response or reaction to substances that are usually not harmful. "Consistent with the lack of a response by TRAV7-2*02 expressing CD8+ T cells, Pd allergy did not develop in mice given B2m−/− Pd-APCs." (PMID 28561797, 2017).
Aminoaciduria (1 paper, 2020). An increased concentration of an amino acid in the urine. "A future prospective study on beta-2 microglobulin, aminoaciduria, hypercalciuria and NGAL as markers of tubular function is therefore recommended." (PMID 32634168, 2020).
amyloidoma (1 paper, 2022). Nodular localized form of amyloidosis with predominantly thoracic localization (pulmonary amyloidosis), considered as secondary protein structure disease in which insoluble protein fibrils accumulate extracellularly. "Amyloid light chain and beta-2-microglobulin are the most common types, with only three previous reports of transthyretin (ATTR) Amyloidoma." (PMID 36109706, 2022).